SOX10 (SRY-box transcription factor 10)
Diseases named in the same sentence as SOX10 in open-access papers (continued):
Sharing a sentence is not in itself a finding about the gene and the disease.
Crohn disease (1 paper, 2025). A gastrointestinal disorder characterized by chronic inflammation involving all layers of the intestinal wall, noncaseating granulomas affecting the intestinal wall and regional lymph nodes, and transmural fibrosis. "In the small intestine of patients with Crohn’s disease, a type of inflammatory bowel disease (IBD), SOX10, PLP1, and S100B transcripts were highly enriched in mucosal glia while GFAP was enriched in various non-glial cells including fibroblasts and immune cells." (PMID 40227232, 2025).
delirium (1 paper, 2018). A disorder characterized by confusion; inattentiveness; disorientation; illusions; hallucinations; agitation; and in some instances autonomic nervous system overactivity. "For delirium, the levels of three proteins differed in serum of affected compared to non-affected patients at uncorrected p < 0.01 (TR4, EZH2, and SOX10) and 15 at p < 0.05." (PMID 30367354, 2018).
dementia (1 paper, 2023). Loss of intellectual abilities interfering with an individual's social and occupational functions. "SM22α-Sox10 axis may be a novel regulator of neurocognitive impairment through modulating VSMC phenotypes and may be a potential control point in dementia." (PMID 37108281, 2023).
diffuse midline glioma (1 paper, 2017). A diffuse glioma that arises from the midline structures of the central nervous system. "Notably, SOX10, a key transcription factor associated with oligodendroglial differentiation and PDGFRA regulation, was up-regulated in both DCG and H3 K27M-mutant diffuse midline glioma, suggesting their developmental and biological commonality." (PMID 28852847, 2017).
DiGeorge syndrome (1 paper, 2023). "A 22q11.21 microdeletion encompassing the TBX1, SHANK3, SOX10, AP1B1, FBXO7, MYH9, and SPECC1L genes cause DiGeorge syndrome, which is associated with DD, ID, seizure, and cardiac malformations, with a prevalence of 1 in 4000." (PMID 37189911, 2023).
embryonal tumors (1 paper, 2021). "Therefore, SOX10 is an appropriate diagnostic marker to discriminate between CNS_NBL and other CNS-PNET/embryonal tumors but it is not sufficient to distinguish them from GBM_MID (sensitivity—92% and specificity 78% for CNS_NBL)." (PMID 33536079, 2021).
endolymphatic hydrops (1 paper, 2025). An accumulation of endolymph in the inner ear (labyrinth) leading to buildup of pressure and distortion of intralabyrinthine structures, such as cochlea and semicircular canals. "In the postnatal stria vascularis, there is impaired normal interaction of SOX9 and SOX10, repressing the expression of the water channel Aquaporin 3, thereby contributing to endolymphatic hydrops." (PMID 40109362, 2025).
endometrial stromal sarcoma (1 paper, 2024). "The lack of any detectable gene fusion and the strong and homogeneous expression of SOX10 and S100 exclude all known genetic subtypes of high-grade endometrial stromal sarcoma (HEESS)." (PMID 39196362, 2024).
esophageal cancer (1 paper, 2014). A primary or metastatic malignant neoplasm involving the esophagus. "Downregulation of SOX10 was frequently detected in 51% (20 of 39) of colorectal, 68% (23 of 34) of gastric and 51% (20 of 39) of esophageal cancer tissues." (PMID 25301735, 2014).
esophageal motility disorder (1 paper, 2022). "With the prolongation of OVA treatment, esophageal motility disorder was aggravated, accompanied by increased eosinophils in the the muscle layer of esophagus and decreased SOX-10-IR cells in the model group." (PMID 36551293, 2022).
esophageal) (1 paper, 2014). "In this study, we found that while SOX10 is ubiquitously expressed in human normal adult and fetal tissues, it is frequently silenced or downregulated due to promoter methylation in digestive (colon, gastric and esophageal) cancer cell lines and primary tumors." (PMID 25301735, 2014).
Exotropia (1 paper, 2022). A form of strabismus with one or both eyes deviated outward. "In summary, we present three separate cases of WS with congenital exotropia and find four novel variants in PAX3, COL11A2 and SOX10 genes." (PMID 36118891, 2022).
hamartoma (1 paper, 2022). A benign and excessive tumor-like growth of mature cells and normal tissues which grow in a disorganized pattern. "We have observed that benign vascular and/or hamartoma-like tumors arise postnatally in mice expressing constitutively active Pik3ca in a mosaic fashion, in cells having expressed the Krox20/Egr2 or Sox10 transcription factors." (PMID 36353506, 2022).
hereditary spastic paraplegia (1 paper, 2017). Hereditary spastic paraplegias (HSP) comprise a genetically and clinically heterogeneous group of neurodegenerative disorders characterized by progressive spasticity and hyperreflexia of the lower limbs. "Of note, there are nine genes among these targets that when mutated are known causes for inherited peripheral neuropathies (IPN) and hereditary spastic paraplegia (HSP) (Inf2, Sox10, Wnk1, Med25, Fa2h, Bscl2, Slc12a6, Kif1a and Kif5a)." (PMID 28077174, 2017).
hyperglycaemia (1 paper, 2023). "A further question arising from this study is whether the reprogramming capacity of cutaneous SCs remains the same, and how the associated biomarkers (e.g. SOX10) are involved in nSCs following nerve damage caused by hyperglycaemia." (PMID 37728731, 2023).
inflammatory myofibroblastic tumor (1 paper, 2025). A multinodular intermediate fibroblastic neoplasm that arises from soft tissue or viscera, in children and young adults. "Additional stains for desmin, αSMA, S100, and SOX10 were all negative, excluding other differential diagnoses such as leiomyoma, schwannoma, granular cell tumor, and inflammatory myofibroblastic tumor (IMT)." (PMID 41328106, 2025).
invasive breast carcinoma (1 paper, 2024). A carcinoma that infiltrates the breast parenchyma. "The invasive breast carcinoma of no special type demonstrated an in situ component, positivity for SOX10 and GATA3, and the patient had no other oncologic history." (PMID 37306115, 2024). "In our cohort of 633 TNBC tumors, a panel consisting of GATA3, mammaglobin and SOX10 similarly identified 96% of all TNBC and 97% of invasive breast carcinomas of no special type." (PMID 37306115, 2024). "Of the 7 invasive breast carcinomas of no special type, 2 were positive for GATA3, 2 were positive for SOX10, and 1 was positive for both GATA3 and SOX10." (PMID 37306115, 2024).
large cell carcinoma (1 paper, 2018). A malignant epithelial neoplasm composed of large, atypical cells. "The HMB45 positive case showed co-expression of SOX10 and was classified as large cell carcinoma." (PMID 30205833, 2018).
leprosy (1 paper, 2023). Leprosy is a chronic infectious disease affecting primarily the skin and peripheral nervous system. "An important question is if piRNAs are downregulated in leprosy biopsies and considering that SCs of peripheral nerves possess genomic plasticity and high regenerate capacity guaranteed by SOX10 and ERBB gene family, why in leprosy the regrowth of axons and SCs is inhibited?" (PMID 38116294, 2023).
leukoaraiosis (1 paper, 2021). "Our results revealed that in addition to SOX10, the expression levels of claudin-1, claudin-3, and myelinogenesis-related proteins were prominently downregulated in leukoaraiosis patients, compared to those in healthy controls." (PMID 34008771, 2021).
liposarcoma (1 paper, 2022). A usually painless malignant tumor that arises from adipose tissue. "The diagnosis was confirmed with immunostaining for S-100, SOX10, and MDM2, which excluded tumors originating from the neural crest and liposarcoma." (PMID 35954639, 2022).
medulloblastoma (1 paper, 2025). A malignant, invasive embryonal neoplasm arising from the cerebellum. "For example, SE heterogeneity analysis has identified SOX10 as the master regulator of the RTK I subtype in glioblastoma, HLX as the master regulator of the Group 3 subtype in medulloblastoma, and LMX1A as the master regulator of the Group 4 subtype in medulloblastoma." (PMID 40361105, 2025).
mucinous adenocarcinoma (1 paper, 2025). An invasive adenocarcinoma composed of malignant glandular cells which contain intracytoplasmic mucin. "Also, mucinous adenocarcinoma is negative for SOX10, S100 and p63." (PMID 40176070, 2025).
multiple system atrophy (1 paper, 2023). Multiple system atrophy (MSA) is a neurodegenerative disorder characterized by autonomic failure (cardiovascular and/or urinary), parkinsonism, cerebellar impairment and corticospinal signs with a median survival of 6-9 years. "Here, αSyn pathology was mainly observed as cellular inclusions, specifically in cases with multiple system atrophy resembling GCIs, which was also shown by double-labelling with a marker for oligodendrocytes using anti-SOX10." (PMID 37640753, 2023).
nephrosclerosis (1 paper, 2007). Hardening of the kidney due to infiltration by fibrous connective tissue (fibrosis), usually caused by renovascular diseases or chronic hypertension. "Average CSX and SOX10 tag methylation was higher in kidneys with benign nephrosclerosis, but the average age of individuals with benign nephrosclerosis was also higher, consistent with the observation that nephrosclerosis is more common in the elderly." (PMID 17672908, 2007).
nerve sheath myxomas (1 paper, 2024). "Although the terms neurothekeoma and nerve sheath myxomas were used interchangeably, they are now described as distinct entities, with the later exhibiting positive immunohistochemistry for S100 and Sox-10 and moderate/diffuse reactivity to glial fibrillary acidic protein (GFAP) and CD57." (PMID 39057135, 2024).
neuroectodermal tumors (1 paper, 2023). "Within neural and neuroectodermal tumors, SOX10 serves as a key player influencing proliferation and differentiation, making it a promising diagnostic and therapeutic marker." (PMID 38132479, 2023). "Studies demonstrating SOX10 expression in neural and neuroectodermal tumors." (PMID 38132479, 2023).
ocular tumors (1 paper, 2022). "To further characterize these tumors, we analyzed a subset of ocular tumors from ONI and control zebrafish for expression of blbp, sox2, and sox10." (PMID 35042909, 2022).
orofacial cleft (1 paper, 2021). A disorder of facial skeleton that is characterized by cleft lip and/or cleft palate that result in feeding, speech and hearing problems caused by failures during development. "Expression of another SOXE transcription factor group member associated with orofacial clefts, SOX10, is not altered upon topiramate treatment, showing specificity for SOX9 upregulation." (PMID 33577554, 2021).
osteosarcoma (1 paper, 2014). A usually aggressive malignant bone-forming mesenchymal neoplasm, predominantly affecting adolescents and young adults. "To investigate the regulation of S100B by SOX10 in Schwann cells, we retrovirally overexpressed SOX10 in primary rat sciatic Schwann cells and rat osteosarcoma ROS cells (top)." (PMID 25536222, 2014).
ovarian adenocarcinoma (1 paper, 2020). An adenocarcinoma that arises from the ovary. "The expression of SOX10 in ovarian adenocarcinoma is significantly higher than that in benign and borderline adenocarcinoma." (PMID 33344444, 2020).
ovarian epithelial tumor (1 paper, 2023). A benign, borderline, or malignant tumor that originates from the surface epithelium of the ovary. "In the context of ovarian epithelial tumors, SOX10 has shown value in differentiating cell origin and estimating prognosis." (PMID 38132479, 2023).
pancreatic adenocarcinoma (1 paper, 2020). "Furthermore, by analyzing the publicly accessible datasets for patients with pancreatic adenocarcinoma (PAAD), we found that the gene expression of three typical SC markers, GFAP, S100B, and SRY-box transcription factor 10 (SOX10), was significantly associated with that of several EMT markers." (PMID 32308766, 2020).
pheochromocytoma (1 paper, 2023). "Pheochromocytomas and abdominal paragangliomas stain positive for neuroendocrine markers CgA, SYP, ISL1, INSM1 and, often, GATA3; subsets of cases may display an intricate network of supporting sustentacular cells which are highlighted by an S100 or SOX10 stain." (PMID 37685605, 2023).
platelet disorders (1 paper, 2020). "Two of the 4 WS4-PCW/PCWH patients were twin siblings, they were naturally conceived and believed to be monozygotic twins based on the history of monochorion and the sharing of similar facial and clinical phenotypes including platelet disorders and the same de novo SOX10 pathogenic allele." (PMID 33362852, 2020).
pubertal delay (1 paper, 2024). "It has been reported that SOX10 gene variants may result in pubertal delay." (PMID 38659011, 2024).
rhabdoid tumor (1 paper, 2024). An aggressive malignant embryonal neoplasm usually occurring during childhood. "Interestingly, even though rhabdoid tumors have been suggested to potentially derive from neural crest cells similar to melanocytes, neither rhabdoid cell lines from DepMap nor ATRT cell lines from our study were dependent on SOX10 or MITF." (PMID 39617889, 2024).
Saethre-Chotzen syndrome (1 paper, 2013). Saethre-Chotzen syndrome (SCS) is an inherited craniosynostosis syndrome characterized by unilateral or bilateral coronal synostosis, facial asymmetry, ptosis, strabismus and small ears with prominent crus, among other less common manifestations. "Twist1 molecularly interacts with Sox10, and although Twist1 S192P displays a comparatively reduced interaction with Sox10 (asterisk, 48.3%+/−5.1%, p-value = 0.002), Twist1 T125;S127A, a Saethre-Chotzen Syndrome-associated Helix I dimerization mutant, does not (102.7%+/−12.0%, p-value = 0.85)." (PMID 23555309, 2013).
schwannomatosis (1 paper, 2023). The least frequent form of the rare genetic disorder neurofibromatosis. "Here, we report identification of somatic mosaicism for SOX10 indel mutations as the genetic alteration underlying a form of segmental schwannomatosis." (PMID 37821623, 2023). "Based on the observations in these two patients, we conclude somatic mosaicism for SOX10 indel mutations causes a form of segmental schwannomatosis lacking other known nerve sheath tumor molecular alterations." (PMID 37821623, 2023).
scoliosis (1 paper, 2022). A congenital or acquired spinal deformity characterized by lateral curvature of the spine. "Compared with uninjected and control-injected embryos, MO-injected Sox10-positive embryos showed skeletal defects, including scoliosis (dashed line) and significantly shortened body length, as well as severely delayed jaw and pharyngeal arch development (lower right-most panel, asterisk)." (PMID 36278547, 2022).
sensorineural hearing loss (1 paper, 2022). "Studies have shown that variants in SOX10 and MITF were identified in some nonsyndromic sensorineural hearing loss (NSHL) cases, which implies the clinical and genetic heterogeneity of this syndrome." (PMID 36329483, 2022).
subependymoma (1 paper, 2024). Subependymoma is a rare and slow growing type of ependymoma, often presenting in middle-aged adults, found more commonly in men than in women, usually located in the fourth and lateral ventricles and manifesting with variable symptoms including headache, nausea, and loss of balance. "The majority of cases presented histopathological and immunohistochemical findings (GFAP immunopositivity without expression of Olig2 or SOX10) suggestive of an ependymal differentiation or subependymoma-like features (microcystic changes)." (PMID 38581034, 2024).
systemic lupus erythematosus (1 paper, 2024). An autoimmune multi-organ disease typically associated with vasculopathy and autoantibody production. "Her condition was considered to be a clinical phenotype 2 of WS with a rare SOX10 variant complicated with systemic lupus erythematosus (SLE)." (PMID 38659011, 2024).
uterine neoplasms (1 paper, 2024). "A series of 7 unclassified uterine neoplasms expressing S100 and SOX10, lacking gene fusions and harboring an activating ERBB2 (HER2) mutation at codon 777 were presented in an abstract form at the USCAP annual meeting." (PMID 39196362, 2024).